NOD2 (nucleotide binding oligomerization domain containing 2)
Diseases named in the same sentence as NOD2 in open-access papers (continued):
Sharing a sentence is not in itself a finding about the gene and the disease.
leprosy (43 papers, 2010 to 2025). Leprosy is a chronic infectious disease affecting primarily the skin and peripheral nervous system. "The most well‐known association between NOD2 variants and mycobacterial infection was reported in 2009 in a genome‐wide association study of leprosy, which was later been successively validated in Vietnam, India, and ethnically mixed Amazonian populations." (PMID 41017210, 2025). "In our analysis of genetic variants associated with leprosy, we found that individuals carrying the heterozygous genotype for the rs2066843 SNP in the NOD2 gene had a higher risk of developing leprosy." (PMID 40435099, 2025). "Contacts carrying the heterozygous CT genotype for the NOD2 SNP had a higher likelihood of developing leprosy when compared to those with the wild-type CC allele (OR = 1.93; 95% CI: 1.01-3.68; p = 0.047)." (PMID 40435099, 2025). "Previous studies have reported associations between NOD2 polymorphisms and leprosy susceptibility, highlighting the potential role of this gene in future research on leprosy susceptibility among contacts." (PMID 40435099, 2025). "Intriguingly, the same LRRK2 coding variants identified in the leprosy family have been implicated in reduced susceptibility to PD and CD while NOD2 R702W is a risk factor for both CD and PD." (PMID 36972292, 2023). "Combined, our results provide insight in the mechanism of leprosy susceptibility and highlight the contribution of specific amino acid alleles in NOD2 and LRRK2 in immune-mediated diseases." (PMID 36972292, 2023). "Allele frequencies of 4 NOD2 SNP in 114 leprosy patients and 456 healthy controls from Norte de Santander, Colombia." (PMID 36877680, 2023). "By applying unbiased WGS analysis on a family with monozygotic twins with extreme early onset leprosy, we identified three coding variants in the LRRK2 and NOD2 genes as strong candidates for contributing to early onset leprosy susceptibility." (PMID 36972292, 2023). "We found three amino acid changes in LRRK2 and NOD2 as candidate susceptibility variants for early onset leprosy." (PMID 36972292, 2023). "While we cannot exclude the presence of additional risk factors, the functional validation of LRRK2 and NOD2 variants implicates these amino acid changes in early onset leprosy." (PMID 36972292, 2023). "Polymorphic variants in the nucleotide-binding oligomerization domain 2 (NOD2) gene are associated with leprosy among populations in a variety of endemic areas around the world." (PMID 36877680, 2023). "This is the first study of a leprosy-endemic region in Columbia to determine which NOD2 gene polymorphisms predispose individuals to leprosy and which protect against it, and to compare these tendencies to those obtained in other parts of the world." (PMID 36877680, 2023). "The loss of pro-inflammatory activity of LRRK2 and NOD2 has been linked to leprosy, PD, and CD, and LRRK2 enhances NOD2-mediated inflammatory cytokine production." (PMID 36972292, 2023). "Several studies have reported that polymorphic variation in the NOD2 gene affects susceptibility to leprosy development, though the nature of the association is population-dependent." (PMID 36877680, 2023). "NOD2 gene polymorphisms have been associated with susceptibility to leprosy and other immune-related diseases." (PMID 36877680, 2023). "The genotype, allele and carrier frequencies of NOD2 rs8057341 confirmed association with protection from leprosy." (PMID 32433683, 2020). "Several genes have been associated with leprosy, such as NOD2, PARK2/PARCG, LRRK2, RIPK2, TNF/LTA/HLA, LACC1, IL10, TLR1, and microRNA (miR)-146a." (PMID 29755459, 2018). "For this reason, the LRRK2 gene is similar to the many critical genes involved in the NOD2-mediated response that is associated with leprosy susceptibility, CD, and Parkinson’s disease (PD)." (PMID 29755459, 2018). "The NOD2 association with leprosy was validated in a Nepalese population, where it was also found associated with leprosy reaction." (PMID 30116885, 2018).
leprosy (continued). "In order to verify the association of polymorphisms in TLR1 and NOD2 genes with leprosy a comparison of allele and genotype frequencies was performed." (PMID 30289892, 2018). "A genomewide association study of leprosy revealed that a polymorphism in the upstream autophagy activator gene NOD2 is a susceptibility factor to develop M. leprae multibacillary infection." (PMID 29643852, 2018). "The relevance of NOD2 in the pathogenesis of leprosy is further suggested by the association of NOD2 gene polymorphisms with susceptibility to leprosy." (PMID 27297389, 2016). "Specific examples include susceptibility loci for inflammatory bowel disorder (IBD) and mycobacterial infection, including at the gene NOD2, where a variant upstream of NOD2 reduces risk of IBD but increases risk of leprosy." (PMID 26702037, 2015). "Several studies have correlated NOD2 gene polymorphisms to leprosy based on its role in the recognition of mycobacteria shortly after signaling mediated by TLRs." (PMID 26793196, 2015). "In this study, we investigated 211 clinically classified leprosy patients and 230 ethnically matched controls in Indian population by genotyping four variants in NOD2 (rs9302752A/G), LRRK2 (rs1873613A/G), RIPK2 (rs40457A/G and rs42490G/A)." (PMID 24015287, 2013). "Furthermore, a genome‐wide association study in 2009 showed that NOD2 is a susceptibility gene for leprosy, which is caused by infection with Mycobacterium leprae or Mycobacterium lepromatosis." (PMID 41017210, 2025). "Notably, the rs2066843 polymorphism in the NOD2 gene was associated with an increased susceptibility to leprosy." (PMID 40435099, 2025). "NOD2 is also known for leprosy susceptibility among the Chinese population." (PMID 38440733, 2024). "In contrast, NOD2 612T, which was present in the affected father and grandmother but not in the twins, and P268S, which was considered to be too common to have a dominant effect on leprosy risk, had been associated with risk of CD." (PMID 36972292, 2023). "Common SNPs in the genomic vicinity of NOD2 have been associated with leprosy in multiple studies." (PMID 36972292, 2023). "Since both LRRK2 and NOD2 had been implicated in susceptibility to leprosy, CD and PD, and the corresponding proteins interact in-vivo in Paneth cells, we considered these two genes high priority candidates for exerting a joint effect on early onset leprosy susceptibility." (PMID 36972292, 2023). "Our results demonstrate how variants in LRRK2 and NOD2 can have a joint effect on different aspects of the immune response which may lead to early onset leprosy." (PMID 36972292, 2023). "Variants near or within NOD2 have previously been associated with leprosy and T1R." (PMID 36972292, 2023). "Also, in the first large-scale GWAS of leprosy, it was discovered that the intracellular pattern recognition receptor gene NOD2 was associated with leprosy in Chinese." (PMID 32373110, 2020). "In like manner, genetic variation at NOD2 is reported to be associated with exacerbated inflammatory responses in leprosy reactions that could modulate downstream pathways, such as LRRK2 activation." (PMID 29755459, 2018). "Polymorphisms in NOD2 are associated with leprosy susceptibility." (PMID 29643852, 2018). "Moreover, the expression of endogenous IL-32 and NOD2 was increased in patients with the restrictive tuberculoid form of leprosy, which is caused by Mycobacterium leprae infection, suggesting that both NOD2 and IL-32 are associated with leprosy." (PMID 30426023, 2018). "Here, we investigated the association of single nucleotide polymorphisms (SNPs) in TLR1 (rs4833095) and NOD2 (rs8057341) genes with susceptibility to leprosy and reported the first association between a genetic variant in TLR1 and sex-specific protection against leprosy." (PMID 30289892, 2018).
leprosy (continued). "We hypothesize that variants in TLR1 and NOD2 genes increase leprosy susceptibility by alterations in pathogen recognition, signaling and pro-inflammatory molecule coding, although these mechanisms may differ between sexes." (PMID 30289892, 2018). "Here, we confirmed the association between IL6 and NOD2 SNPs and leprosy reactions among Brazilians, and demonstrated that the NOD2 genotype associated with a decreased risk for developing a reaction is also related to lower levels of IL-6 in the sera of non-reactional patients." (PMID 28715406, 2017). "Our finding that LRRK2 modulates Nod2 signaling in macrophages may explain how LRRK2 is involved in leprosy susceptibility." (PMID 27830463, 2017). "Consistent with this hypothesis, single-nucleotide polymorphisms in the NOD2 gene have implicated this PRR as the key innate immune receptor that contributes to host defense in leprosy." (PMID 27297389, 2016). "Another study in 933 patients (240 patients had reversal reactions and 124 had ENL reactions) of Nepal compared with 101 controls, suggested that NOD2 genetic variants are associated with susceptibility to leprosy and the development of leprosy reactive states." (PMID 26793196, 2015). "Three NOD2 alleles of rs8057341 (A allele, Pc = 0.003), rs2111234 (G allele, Pc = 0.031), and rs3135499 (C allele, Pc = 0.023) were statistically significant in family-based study association, indicating protection to leprosy." (PMID 26793196, 2015). "Two SNPs in the NOD2 gene were found to be associated with leprosy in a study of 706 Han Chinese patients and 1226 healthy controls: rs9302752 (OR = 2.28; IC = 1.70–3.06) and rs7194886 (OR = 2.25; IC = 1.58–3.21) suggesting risk for development of leprosy." (PMID 26793196, 2015). "Dysregulation in NOD2 signalling is associated with pathogenesis of many inflammatory disorders and is also associated with triggering of IL-32 dependent dendritic cell programming in leprosy." (PMID 24015287, 2013). "In addition, the studied NOD2 variant (rs9302752A/G) was associated with susceptibility to tuberculosis and leprosy in Chinese and Vietnamese population." (PMID 24015287, 2013). "Mutations in the NOD2 locus are highly associated with CD in Europeans and a recent genome-wide study from China has shown that a high proportion of leprosy patients have many of the same genetic mutations found in patients with CD including NOD2/CARD15 mutation." (PMID 22742424, 2012). "However, the functional properties of the NOD2 gene variants herein described and their relationship to the pathophysiology of leprosy remain unknown." (PMID 36877680, 2023). "Therefore, this study aimed to identify any associations between the rs3135499, rs2111234, rs8057341, and rs7194886 SNPs in the NOD2 gene and susceptibility to leprosy in a sample of leprosy patients and healthy individuals from this region in northern Colombia." (PMID 36877680, 2023). "The aim of this study was to analyze the rs7194886, rs2111234, rs3135499, and rs8057341 single nucleotide polymorphisms (SNPs) in the NOD2 gene using a case-control study to determine whether they confer greater or lesser susceptibility to the development of leprosy." (PMID 36877680, 2023). "Thus, the leprosy susceptibility loci, including NOD2, RIPK2, TNFSF15, LACC1, LRRK2, IL12B, and HLA‐DR in phagocytes and IL23R, TYK2, and CSK in T cells, may interfere with the synergistic antimicrobial response between phagocytes and T cells." (PMID 38020709, 2023). "Nevertheless, NOD2 dependence was demonstrated in the immune response to M. leprae and M. leprae-specific murodipeptides (containing glycine instead of alanine and with variable amidation of the glutamate residue), providing grounds for the genetic associations with leprosy." (PMID 37262021, 2023).
leprosy (continued). "Similarly, Sales-Marques and coauthors (2014), in a meta-analysis with population samples from different Brazilian regions combining case-control and family-based studies, confirmed that the A allele of NOD2 (rs8057341) is a genetic resistance factor for leprosy." (PMID 32433683, 2020). "The final model for leprosy included contact characteristics, consanguinity with the index case, and the SNP rs2066843 in the NOD2 gene." (PMID 40435099, 2025). "NOD2 and RIPK2 mRNA were found to be up-regulated 3- to 4-fold in skin tissue samples from people with leprosy compared to controls, and the frequency of NOD2-positive cells was 3 times higher in tuberculoid than in lepromatous lesions." (PMID 37262021, 2023). "Since leprosy is an infectious disease, a weakened inflammatory host response mediated by the LRRK2 DM and NOD2 R702W is expected to increase susceptibility." (PMID 36972292, 2023). "NOD2 interacts with the adaptor protein kinase RIPK2 for signaling, and mutations in both NOD2 and RIPK2 have been associated with leprosy and/or its endophenotypes." (PMID 37262021, 2023). "While our study was motivated by early onset leprosy, it is likely that the additive interactions of the LRRK2 and NOD2 variants and their effect on key inflammatory host pathways are also valid in PD and CD patients." (PMID 36972292, 2023). "In leprosy, a human mycobacterial infection, IL-32 has been shown to promote the differentiation of monocytes into CD1b+ DCs upon NOD2 activation." (PMID 37727785, 2023). "Accordingly, the expression of NOD2 and IL-32, as well as the number of CD1b+ DCs were higher in tuberculoid than in lepromatous leprosy lesions, indicating a relevant mechanism to control the dissemination of infection." (PMID 37727785, 2023). "We validated NOD2 and IFNG associations with resistance and risk of leprosy, respectively, in the Amazon ethnic admixed population." (PMID 32433683, 2020). "The role of NOD2 in leprosy immune response was also functionally confirmed by cell-based experiments." (PMID 32373110, 2020). "In a family-based Vietnamese sample, 16 significant GWAS SNPs were tested for association and SNPs tagging HLA-DR–DQ, RIPK2, NOD2 and CCDC122–LACC1 were validated as risk factors for leprosy susceptibility." (PMID 30116885, 2018). "Two SNPs located in NOD2 and CCDC122-LACC1 were associated with leprosy and were subsequently replicated in three independent Brazilian case-control population samples." (PMID 30116885, 2018). "In total, 15 SNPs located in five loci—HLA-DR–DQ, RIPK2, TNFSF15, NOD2 and CCDC122-LACC1—were significantly associated with leprosy (p < 1.00 × 10−10)." (PMID 30116885, 2018). "NOD2 involvement in leprosy was first identified in a GWAS and later replicated; in addition, association of NOD2 variants with leprosy reaction has been detected." (PMID 30079069, 2018). "From the results, we conclude that SNPs at the NOD2 and IL6 genes are associated with leprosy reactions as an outcome." (PMID 28715406, 2017). "Cox models showed associations between the SNPs rs751271 at NOD2 and rs2069845 at IL6 with leprosy reactions (HRGT = 0.45, p = 0.002; HRAG = 1.88, p = 0.0008, respectively)." (PMID 28715406, 2017). "Stimulation through NOD-2 efficaciously differentiates human monocytes to DCs in experimental model of leprosy and substantially improves their ability to cross-present antigen to CD8 T cells." (PMID 27265209, 2016). "Summary of associations between genes of innate immune response TLR, NOD2, PARK2, PACRG, and leprosy." (PMID 26793196, 2015). "A recent genome wide study in Chinese leprosy patients has provided vital insights on the role of NOD2 (rs9302752A/G), LRRK2 (rs1873613A/G) and RIPK2 (rs40457A/G and rs42490G/A) variants in regulating the leprosy infection." (PMID 24015287, 2013). "Distribution of investigated NOD2, RIPK2, and LRRK2 variants in clinically classified leprosy patients and controls." (PMID 24015287, 2013).
leprosy (continued). "Cellular experiments confirmed the contribution of NOD2 in the immune response in leprosy." (PMID 38440733, 2024). "In this analysis we included variants associated with leprosy susceptibility at genome-wide significance in other populations, alongside variants at LRRK2 and PRKN, and pathogenic variants at NOD2." (PMID 36121873, 2022). "In monocyte, recognition of NOD2 by leprosy muramyl dipeptide could induce the expression of IL-32, which regulates the differentiation from monocyte to CD1b+ DC." (PMID 32373110, 2020). "Here, we investigated whether SNPs located in eleven genes: CCDC122/LACC1, IFNG, IL6, IL10, IL23R, LRRK2, NOD2, PACRG/PRKN, TLR1, TNF and TYK2 are associated to leprosy susceptibility in a population in the North of Brazil." (PMID 32433683, 2020). "The markers included 11 SNPs selected to replicate the previously reported associations of the TLR1, NOD2, and IL6 genes and the remaining SNPs in 4 candidate genes TNF, LTA, IFNG, and IL10, in reference to markers previously associated with leprosy per se as an outcome." (PMID 28715406, 2017). "NOD2 recognition of MDP triggers the induction of specific inflammatory responses to combat bacterial infection, including the production of IL-32, which in leprosy is linked to host defense against the pathogen M. leprae." (PMID 27297389, 2016). "Together, these data indicate that M. leprae MDP, despite its unique structure, activates human monocytes via NOD2 to trigger a range of innate immune responses with relevance to the pathogenesis of leprosy which are comparable to those induced by the MDP structures found in most other bacteria." (PMID 27297389, 2016). "Pathogenesis routes in leprosy initiate with the recognition of pathogen-associated molecular patterns (PAMPs) from M. leprae by pattern recognition receptors (PRRs) and mycobacterial uptake (TLR, NOD2 and MRC1)." (PMID 23798993, 2013). "Consequently, LRRK2 DM and NOD2 R702W had a cumulative effect on the reduction of N-glycolyl MDP-induced NF-κB activation and the variants carried by the early onset leprosy twins reduced NF-κB activation by approximately half compared to the wild-type variants expected in the general population." (PMID 36972292, 2023). "Evaluation of the genetic link between NOD2 and TB may require a better definition of TB endophenotypes due to the nature of PRRs’ subtle modifications of immune responses, as has been done for leprosy." (PMID 37262021, 2023). "Given the presence of additional strong candidates in the NOD2 vicinity (e.g. SNX20) and the notorious difficulties in identifying the gene target of common SNPs (LD, long range enhancer effects), our results are the first to implicate directly NOD2 in leprosy susceptibility." (PMID 36972292, 2023). "But knowledge about effect of variants on function of NOD2 was still absent in leprosy." (PMID 32373110, 2020). "NOD2 has been implicated in the pathogenesis of human leprosy, yet it is not clear whether Mycobacterium leprae, which has a distinct MDP structure, can activate this pathway." (PMID 27297389, 2016). "However, the NOD2 rs9302752A/G variant was not in Hardy-Weinberg equilibrium in Indian clinically classified leprosy patients and marginally significant in control group." (PMID 24015287, 2013). "In contrast to Han Chinese population we observed that NOD2 rs9302752A/G variant was not in Hardy-Weinberg equilibrium in studied Indian population, therefore the contribution of this variant to leprosy susceptibility remains unclear." (PMID 24015287, 2013). "We investigated the possible association of gene variants NOD2 (rs9302752A/G), LRRK2 (rs1873613A/G) and RIPK2 (rs40457A/G and rs42490G/A) that are vital for NOD2 signalling and subsequent activation of the NF-kB complex in a cohort of clinically classified leprosy patients." (PMID 24015287, 2013).